CXCL12 (C-X-C motif chemokine ligand 12)
Diseases named in the same sentence as CXCL12 in open-access papers (continued):
Sharing a sentence is not in itself a finding about the gene and the disease.
tumor (continued). "Several studies have shown that some tumor cells, in addition to expressing CXCR4, can secrete CXCL12 and so activate an autocrine loop promoting growth and metastasis." (PMID 28055968, 2017). "To elucidate the functional role of the Cxcl12/Cxcr4 axis in antral tumorigenesis, we generated Tie2-Cre; Cxcl12flox/flox mice with targeted deletion of Cxcl12 in endothelial cells, and used these animals in the MNU tumor model." (PMID 29340033, 2017). "SDF-1 (or, CXCL12) is a chemokine expressed in certain cancers, involved in tumor cell migration and metastasis." (PMID 29254283, 2017). "Among tumor-derived individual signals, our study suggests potential key roles for S100A9 and CXCL12 among others." (PMID 28472073, 2017). "Compared to NS group, oral administration of QRHX dramatically attenuated the increased expressions of CXCL12 and CXCR4 in tumor tissue (P < 0.01)." (PMID 28630636, 2017). "Inflammatory chemokine CXCL12 of enriched organs forms a concentration gradient and attracts CXCR4 positive tumour cells to homing by directed movement." (PMID 28403883, 2017). "Additional studies are required to determine if BH3 mimetic suppression of CXCL12 is limited to MPNST and related tumor cells or is a general phenomenon with implications for other tumor types." (PMID 28055968, 2017). "We cover fundamental molecular players in the tumor microenvironment including extra- (CCL2, CSF-1, CXCL12, IL-4, IL-13, semaphorins, WNT5A, and WNT7B) and intracellular signals." (PMID 28197019, 2017). "TAM derive from circulating monocytes, which are recruited into the substance of the tumor by a wide range of chemokines, especially MCP-1/CCL2, CXCL1, CXCL10 and SDF-1/CXCL12, released either by tumor cells or other stromal cells." (PMID 28098760, 2017). "CXCL12, CXCR4, JAK2, and STAT3 can not only play significant role in tumor cell or macrophage, but also other cells, such as T lymphocyte, neutrophils, tumor-associated fibroblast, and endothelial cells." (PMID 28630636, 2017). "The CXCL12/CXCR4 axis is related to mediating tumour cell invasion and proliferation and plays an important role in tumour angiogenesis, progression and metastasis." (PMID 28386296, 2017). "It demonstrates that the EMT-promoting signals conveyed by CXCL12 to NET cells are critically sensed by surface CXCR4 leading to transcriptional, structural and functional modifications that culminate in enhanced tumor osteotropism." (PMID 28186979, 2017). "Chemokines and cytokines including CCL2, CXCL12, CSF1, CCL5, CCL22, IL6 and TGFB3 are secreted by primary tumor cells to recruit immune cells to escape from anti-tumor immune responses." (PMID 28591712, 2017). "Forward selected, proportional Cox regression of survival modifying parameters (T, N, R, G, tumor localization, MMP2/9, TIMP1/2, CXCR4, and CXCL12) identified CXCR4 being the only survival-modifying parameter in HNSCC." (PMID 29348861, 2017). "The CLL microenvironment supports tumor cell survival via secretion of a number of soluble and surface-bound factors, including CXC chemokine ligand 12 (CXCL12)." (PMID 29379494, 2017). "CXCL12, CCL17 and CCL22 play a role in the recruitment of T-regs to tumour sites and thereby inhibition of anti-tumour response." (PMID 28987144, 2017). "CXCL12, as one of the CXC chemokines, was previously shown to be involved in chronic inflammation, chemotaxis, and tumor development via its specific receptor CXCR4." (PMID 28938626, 2017). "CXCR4/CXCL12 axis triggers PI3K-Akt and Ras-Erk signalling pathways, which mediates tumor cells survival and proliferation." (PMID 28793338, 2017). "In vitro and in vivo studies also have shown a correlation between tumor metastasis and alterations in CXCR4/CXCL12 signaling in PDAC." (PMID 28356064, 2017).
tumor (continued). "C-X-C motif chemokine ligand 12(CXCL12), also termed stromal cell-derived factor 1(SDF-1), is a member of the CXC chemokine subfamily that plays a role in immune surveillance, inflammation response, tumor growth and metastasis." (PMID 28272462, 2017). "Intranodal lymphatic sinuses are also greatly influenced by CCR7-CCL19/CCL21, CXCL12/CXCR4, S1P, IL-7, IFN-γ, integrin α4β1, and TGF-β in tumor microenvironment." (PMID 28036019, 2016). "Another process by which the CXCR4/CXCL12 axis contributes to GBM growth is its ability to recruit endothelial and marrow cells to support tumor vasculogenesis and angiogenesis." (PMID 26977157, 2016). "If we analyze the relationship between serum levels of proteins tested and histological type of EC, the serum concentrations of CXCL12 were significantly higher in patients with ESCC than in control group, similarly to classical tumor markers and CRP." (PMID 27041792, 2016). "By Kaplan-Meier method and log-rank test, high CXCL12 and CXCR7 expressions in tumor tissues predicted poor overall survival in two cohorts (P=0.040 and =0.037 for CXCL12; P=0.007 and =0.020 for CXCR7)." (PMID 27542220, 2016). "However, it has been shown that CXCL12/CXCR4 might be expressed also in many tumor cells." (PMID 27041792, 2016). "However, in the aggressively growing tumor cell line, receptor activity could be protected by the upregulation of the neutral ligand Cxcl5 (32-fold relative to vGPCR-3T3) that competes with the antagonist CXCL12 for receptor binding." (PMID 26871287, 2016). "The main molecules involved in HSC and tumour cell migration are couple chemokine (C–X–C) receptor type 4 (CXCR4) and 6 (CXCR6) and their respective ligands, C–X–C motif chemokine ligand 12 (CXCL12) and 16 (CXCL16)." (PMID 27782035, 2016). "CXCL12 contributes to tumor immune escape, by inducing the migration of CXCR4+ regulatory cells, including MDSCs and Tregs toward CXCL12-rich tumor microenvironment." (PMID 27590504, 2016). "We also examined the effects on tumor-promoting markers related to Treg cells, including CCL22, CXCL12 and FoxP3." (PMID 26956047, 2016). "Monocyte infiltration into a tumor is mediated by chemokines (e.g., CCL2, CCL5, and CXCL12), CSF-1, and components of the complement cascade." (PMID 26980947, 2016). "The chemokine receptor 4 (CXCR4) and its only known natural ligand stromal cell derived factor-1 (SDF-1, CXCL12) have gained considerable attention in oncology, in particular its impact on tumor metastasis." (PMID 27655427, 2016). "In this study, we analysed the relationship between CXCL12/CXCR4 expression and tumor proliferation in patients with ESCC." (PMID 27439769, 2016). "Purified B effector cells kill tumor cells directly and such killing involves not only the Fas/FasL pathway, but also the CXCR4/CXCL12 pathway and perforin." (PMID 27528023, 2016). "Since both HSCs and PC cells use the CXCL12/CXCR4 axis for occupying the osteoblastic niche, plerixafor inhibited CXCL12/CXCR4 interactions, leading to reduced tumor growth when given at the time of tumor implantation." (PMID 27809841, 2016). "In this regard, we have shown that CDDO-Me impedes TAM recruitment to tumors in PyMT mice through inhibition of tumor cell production of CCL2 and CXCL12." (PMID 26918785, 2016). "FN1, SPP1, CXCL12 and vitronectin (VTN) are known to promote the survival and migration of tumor cells." (PMID 27329720, 2016). "CXCL12 was expressed in tumor cells and in tumor vessels; CXCR7 was expressed by tumor and endothelial cells in the primary tumor and in the brain metastasis." (PMID 27018053, 2016). "More importantly, RCC samples showed a decreased expression of CXCL12 and increased expression of CXCR4, compared to their respective adjacent normal kidney tissue, revealing a role in tumor progression." (PMID 27293448, 2016).
tumor (continued). "CXCL12 is the reason for immune suppression, while abrogation of FAP α positive cells permits immune inhibition of tumor growth and enhances the efficacy of constructed immunotherapeutic antibodies." (PMID 26985769, 2016). "CXCL12/CXCR4 transactivates members of growth factor receptor in PC cells, and expression of HER2 in PC patients correlates with tumor cell proliferation and activates androgen receptor signaling in advanced disease." (PMID 27809841, 2016). "Previously, we showed that activation of the CXCL12/CXCR4 axis transactivates HER2 and promotes intraosseous tumor growth." (PMID 27809841, 2016). "It was found that some of the flowing tumor cells stopped and attached to HUVEC cells when they passed over the top of the organ chambers containing CXCL12." (PMID 27191997, 2016). "Since CXCR4 has been reported to mediate tumor cell invasion and metastasis, we performed chemotaxis assays to examine the capacity of GC cells to migrate in response to SDF-1α (CXCL12), a specific ligand for CXCR4." (PMID 27007162, 2016). "CXCR4, a receptor for the stromal cell–derived factor-1 (CXCL12/SDF-1α), promotes tumor progression, angiogenesis and drug resistance." (PMID 31656694, 2016). "CXCL12/CXCR4 can directly influence the proliferation, migration and invasion of CXCR4-expressing tumor cells [reviewed in Ref 30]." (PMID 27590504, 2016). "If we consider the association between serum levels of proteins tested and histological type of EC, the concentrations of CXCL12 were significantly higher in patients with ESCC than in control group, similar to classical tumor markers and CRP." (PMID 27041792, 2016). "When these cells were exposed for 24 hours to a hypoxia-inducing treatment (100 μM CoCl2) as a tumor-relevant stressor and then treated with Bay60-6583 for another 24 hours, the expression of both FGF2 and CXCL12 increased." (PMID 27590504, 2016). "HPV-positive tumor tissue-derived cell cultures produced much higher levels of chemokines, namely CXCL9, CXCL10, CXCL12, CCL17 and CCL21." (PMID 25949860, 2015). "Another study suggests that under severe hypoxic conditions tumor cells elevate CXCR4, which allows them to migrate towards a gradient of CAF induced CXCL12 and escape to a normoxic environment at a distant site." (PMID 26501341, 2015). "The data reveals that both CXCL12 expression by fibroblasts and CXCR4 expression on cancer cells, within hypoxic areas of tumors, trigger tumor cell growth, motility and invasiveness." (PMID 25669980, 2015). "HPV-positive tumor tissue-derived cell cultures produced markedly higher levels of chemokines, namely CXCL9, CXCL10, CXCL12, CCL17 and CCL21, and slightly higher levels of the cytokines IL-2, IL-17, IL-23 and IFNγ." (PMID 25949860, 2015). "In conclusion, our results indicate a mutual tropism and paracrine interaction between nerves and cancer cells: peripheral nerve-derived CXCL12 stimulates the proliferation and invasion of CXCR4-positive tumor cells." (PMID 25605248, 2015). "An optimum dose gradient of CXCL12 conducted by the neurons and Schwann cells induces the chemotactic migration of CXCR4-bearing tumor cells toward the peripheral nerves, and simultaneously increases PCa cells metastasis and invasion, thereby establishing PNI." (PMID 25605248, 2015). "As a result of binding to its unique chemokine ligand, CXCL12, CXCR4 is known to activate G protein-mediated signaling cascades, leading to tumor proliferation, survival, angiogenesis, and chemotaxis in multiple cancers." (PMID 25955316, 2015). "A role for CXCR4 signaling in HSA metastasis is possible, but the origin of CXCL12 as an autocrine, paracrine or endocrine factor, as well as the role of CXCR4 expressed in inflammatory and stromal cells that form the tumor niche remain to be determined." (PMID 29061949, 2015). "This receptor and its ligand, CXCL12, also known as stromal cell-derived factor-1 (SDF-1), appear to play a role in tumor metastasis." (PMID 26729169, 2015).
tumor (continued). "CXCR4 selectively binds to CXC chemokine stromal cell-derived factor 1α (SDF-1α or CXCL12), and CXCL12/CXCR4 signaling is regarded as a candidate factor involved in the tumor-stromal interactions." (PMID 25605248, 2015). "Stromal cell derived growth factor 1 (SDF-1), or CXCL12, is frequently expressed by TME of multiple tumor types." (PMID 25588753, 2015). "CAF-derived chemokines CXCL-12 or CXCL-14 recruit bone marrow-derived cells, macrophages, and other immune cells into the tumor microenvironment, enabling tumor growth." (PMID 25853091, 2015). "Chemokines CXCL1, CXCL2 and CXCL12 have been proved to play important roles in the growth of various cancers by activating MAPK/ERK signaling pathway and thus promote tumor cell proliferation." (PMID 26313265, 2015). "Given that the CXCL12/CXCR4 axis is considered to be a critical mediator of cancer–stroma interactions, our study also supports the important contributions of the tumor microenvironment to EGFR cross-talk with other signaling pathways in PDAC." (PMID 25679210, 2015). "Epigenetic mechanisms like demethylation of CXCR4 and hypermethylation of CXCL12 and ESR1 are a characteristic of tumor stage, size, metastasis, and poor overall survival." (PMID 25814785, 2015). "Cells in the tumor microenvironment, including both tumor cells and stromal cells, overexpressed chemokines such as CCL2 (MCP-1), CXCL12 (SDF-1), CCL9 (MIP-1γ) and/or CCL18 (PARC), and recruit MOs into the tumor bed." (PMID 26155942, 2015). "Inactivation of NF-κB, STAT3, or HIF-1α, neutralization of CCL2 or CXCL12, or TAM depletion results in disrupted angiogenesis and decreased tumor growth, highlighting the critical role of inflammatory mediators in tumor angiogenesis." (PMID 26501341, 2015). "In pancreatic cancer, tumor cells secrete CXCL8 and CAFs secrete CXCL12 to enhance the recruitment and proliferation of ECs." (PMID 25110692, 2014). "These interactions represent an indirect mechanism mediating CXCL12/CXCR4-dependent promotion of survival, proliferation and migration of tumor cells." (PMID 24904289, 2014). "A previous study showed that CXCL12/CXCR4 axis signaling induces actin stress fiber formation, and regulates tumor spread and metastasis." (PMID 25121739, 2014). "Stromal fibroblasts support the growth of neoplastic cells through elevated secretion of CXCL12, and integrins induce expression of CXCR4 and growth-factor receptors sustaining a pro-survival loop for tumor cells." (PMID 24904289, 2014). "High CXCL12 levels in the tumor attract CXCR4-positive inflammatory, vascular and stromal cells into the tumor mass, where they will eventually support the tumor growth by secreting growth factors, cytokines, chemokines, and pro-angiogenic factors." (PMID 25471741, 2014). "CXCR4 is considered to be the major chemokine receptor expressed on cancer cells and its expression is required for tumor metastasis to other organs; CXCR4 activation by CXCL12 induces the migration of neoplastic cells." (PMID 24348776, 2014). "The significance of the CXCL12/CXCR4 signaling axis in breast and other tumor progression and invasiveness has been reported by many investigations (6, 16, 17 and 18)." (PMID 25237365, 2014). "Further research has emphasized the key role of CXCR4 in tumor cell malignancy; the activation of CXCR4 by CXCL12 has been shown to induce the migration, invasion and angiogenesis of tumor cells." (PMID 25268356, 2014). "CXCL9, CXCL10, CXCL12 and FSP1 production by CAFs promote recruitment of T lymphocytes into the tumor; however the number of cytotoxic T cells versus tumor suppressive cells is shifted." (PMID 24978438, 2014). "The previous views also suggested that tumor cells express high CXCR4, and the metastasis-targeted organs express high CXCL12, so the tumor cells were attracted to the ligand in these organs." (PMID 24810923, 2014).
tumor (continued). "In this study we assessed the effect of inhibition of the CXCL12/CXCR4 pathway by a novel CXCR4 antagonist, CTCE-9908 on in vitro cell proliferation and invasion, and in vivo orthotopic tumor growth, metastasis, and angiogenesis of PC cells." (PMID 24472670, 2014). "In four MCC specimens analysed, multicolour CFM demonstrated CXCL12 expression in stromal and endothelial cells that co-located with CD8+ cells separate to tumour cells." (PMID 24961933, 2014). "Within the chemokines in cancer, the CXCR4/CXCL12 axis is currently best characterized and CXCR4 is a ubiquitously expressed receptor on tumor cells." (PMID 25254213, 2014). "Experimentally, proof of principle studies demonstrated that inhibition of CXCL12-evoked CXCR4 signaling by respective blocking agents inhibited metastasis in experimental models, achieved by intravenous tumor cell injection." (PMID 24390633, 2014). "We also demonstrated that the CAFs-MM cell interaction involves CXCL12/CXCR4 pathway and several integrins confirming the importance of contact between tumor and stromal cells." (PMID 24978438, 2014). "A growing body of evidence has demonstrated that the CXCL12/CXCR4 axis and Rho signaling pathway play critical roles in cell migration, chemotaxis, tumor metastasis, and actin stress fiber formation." (PMID 25121739, 2014). "Pharmacological inhibition of HIF1α or the CXCL12/CXCR4 axis reduced BM-derived cell recruitment and prevented tumor recurrence." (PMID 25526031, 2014). "In particular, CXCL12, through its receptors CXCR4 and CXCR7, affects tumor progression by controlling cancer cell survival, proliferation and migration, and, indirectly, via angiogenesis or recruiting immune cells." (PMID 24904289, 2014). "The stroma-secreted chemokine, stroma derived factor 1α (SDF-1α, or termed as CXCL12), and its cognate receptor, the chemokine receptor 4 (CXCR4) are two very key mediators in the cross-talking between tumor cells and their microenvironment." (PMID 25312253, 2014). "CXCL12 (previously known as stromal cell-derived factor-1, SDF-1) is an exception to this characterization, since it is ELR− but mediates tumor-promoting angiogenesis via its receptor CXCR4." (PMID 25484899, 2014). "This unexpected finding prompted a detailed immunohistochemical analysis of the auriculum cordis and of the lung for expression of endogenous CXCL12 as a chemo-attractant for CXCR4 and even more for CXCR4/CXCR7 co-expressing tumor cells." (PMID 24040160, 2013). "All SHH tumors demonstrate co-overexpression of CXCL12 and CXCR4, with the exception of one tumor that was obtained after treatment with high-dose chemotherapy." (PMID 23497290, 2013). "The subsequent CXCL12/CXCR4 signaling also enhances cell survival via Akt activation, thereby providing an advantage to newly arrived tumor cells in the bone microenvironment." (PMID 26237063, 2013). "The chemokine (C-X-C motif) ligand 12 (i.e., CXCL12), also known as stromal cell-derived factor-1 (SDF-1), is expressed by tumor cells, fibroblasts and ECs within the tumors." (PMID 24314323, 2013). "Of these overexpressed genes, 5 (CXCR4, CXCL12, MMP2, MMP9 and MMP13) were selected on the basis of their strong correlation with tumor metastasis and were validated by qPCR." (PMID 24179538, 2013). "In fact, hypoxia affected the localization of both tumor and stromal cells by up-regulating their expression of CXCR4 receptor, CXCR4 ligand, and CXCL12." (PMID 23533994, 2013). "Whereas in tumor-bearing mice groups, most of cytokines were decreased after LF-MF exposure, including KC, CCL1, IFN-γ, CXCL9, CXCL12, TREM-1, CCL12, IL-1rα and IL-16." (PMID 24314291, 2013). "The addition of CXCL12 or CCL18 immunoneutralizing antibody in the co-culture system of CAFs and MDA-MB-231 reduced tumor cell invasion by nearly 60%." (PMID 23577100, 2013). "CXCR4 is the receptor of SDF1/CXCL12, and their interaction promotes increased tumor cell proliferation and survival." (PMID 23762835, 2013).